IL6 (interleukin 6)
Diseases named in the same sentence as IL6 in open-access papers (continued):
Sharing a sentence is not in itself a finding about the gene and the disease.
migraine (continued). "The number of monthly migraine headache days was positively correlated with serum LPS, HIF-1α, VE-cadherin, and IL-6 levels, HADS-A, HADS-D, HIT-6, and MigSCog scores." (PMID 38369488, 2024). "The evaluation of the combined effects of ω-3 fatty acids and nano-curcumin supplementation on IL-6 gene expression, serum level, and hs-CRP levels in migraine patients." (PMID 38770523, 2024). "The number of monthly migraine headache days was correlated with serum levels of LPS, HIF-1α, VE-cadherin, and IL-6." (PMID 38369488, 2024). "included 10 studies with a total of 1842 participants, revealing significant elevations in serum CRP, IL-1β, IL-6, and TNF-ɑ levels among migraine patients, thus supporting the inflammation-related mechanisms proposed in this study." (PMID 39850553, 2024). "Elevated levels of pro-inflammatory cytokines, such as interleukin-1 beta (IL-1β), interleukin-6 (IL-6), and tumor necrosis factor-alpha (TNF-α), have been observed in the blood and cerebrospinal fluid of individuals experiencing migraine attacks." (PMID 39107712, 2024). "Similar to our findings, previous studies indicated higher expression levels of proinflammatory cytokine genes or proteins (e.g., IL-1β, IL-6, and TNF-α) in the peripheral blood and trigeminovascular region of animals with NTG-induced migraine." (PMID 38612517, 2024). "In the ACC, the expression levels of IL-1β, IL-6, and TNF-α were higher in the NTG-induced migraine groups than in the VEH group; proinflammatory cytokine expression was significantly higher in the CM group than in the EM group." (PMID 38612517, 2024). "The results indicated increased expression of proinflammatory cytokines (IL-1β, IL-6, and TNF-α) in the Sp5C regions of NTG-induced migraine groups compared with the VEH group; expression levels were significantly higher in the EM group than in the CM group." (PMID 38612517, 2024). "Elevated levels of the pro-inflammatory cytokines IL-6, IL-8, and TNF-α are commonly observed in patients with migraine." (PMID 37098498, 2023). "The two most commonly measured cytokines (IL-6 and TNF-α) were both higher in migraine than controls." (PMID 37016284, 2023). "Consistent with our research, some studies have found that the transcriptional activity of inflammatory cytokines (IL-6 and TNF-α) and CGRP was increased in trigeminal ganglia, cervical medulla, and pons in NTG-induced migraine model." (PMID 37090989, 2023). "The proinflammatory cytokines IL-6, TNF-α, and IL-8 are higher in patients with migraine than healthy controls, and IL-1β levels are raised during migraine attacks." (PMID 37016284, 2023). "SD as the electrophysiologic event underlying migraine attacks has been demonstrated to further temporarily upregulate pro-inflammatory cytokines such as IL-6, IL-1β and TNF-α during migraine attacks." (PMID 37596546, 2023). "A recent in vivo study induced a rat migraine model with dural electric stimulation and found an increase in serum inflammatory factors, including IL-1β, TNF-α and IL-6." (PMID 37190506, 2023). "Proinflammatory cytokines, such as interleukin (IL)-1β, IL-6, and tumor necrosis factor-alpha (TNF-α), as well as anti-inflammatory cytokines, such as IL-10, are elevated in patients with migraine and are suggested to play a role in migraine." (PMID 36362765, 2022). "XZR reduced the degranulation of mast cells as well as the levels of CGRP, SP, NO, and proinflammatory cytokines, including TNF-α, IL-1β, and IL-6, suggesting that XZR improved migraine by relieving the neurogenic inflammatory response." (PMID 35928284, 2022). "RANTES, TRP/LNAA, KYN/TRP, IL6, TNFa, and MCP-1 showed greater VIP score than 1, indicating relevance in migraine diagnosis." (PMID 35883701, 2022). "Altered levels of pro-inflammation cytokines in plasma and serum, such as interleukin 1 beta (IL-1β), interleukin 6 (IL-6), and tumor necrosis factor alpha (TNF-α), has been demonstrated the correlation to migraine in both patients and animals." (PMID 35033010, 2022).
migraine (continued). "The role of cytokines in migraine is evidenced by the effectiveness of NSAIDs in symptomatic therapy, by the presence of ictal and interictal increased plasma levels of TNF-α and IL-6 and increased levels of TNF-α in CSF." (PMID 36614097, 2022). "The body of migraine patients was in a state of microinflammation, and the serum levels of TNF‐α, IL‐6, and hs‐CRP were at a high level." (PMID 35791513, 2022). "These reactions can further increase the inflammatory cytokines (such as 5-HT, IL-6, and TNF-α) in cerebral microvascular endothelial cells, and finally lead to migraine." (PMID 36619923, 2022). "Meanwhile, previous studies have found that inflammation plays an important role in the pathophysiology of migraine, and the levels of serum inflammatory cytokines, such as CRP, IL-1β, IL-6, and TNF-α are higher in migraineurs compared with healthy controls." (PMID 35493816, 2022). "One study showed that migraine patients have higher levels of interleukin 1-beta (IL1-β) and interleukin-6 (IL6), and lower levels of interleukin-10 (IL10) compared to healthy control patients." (PMID 35432179, 2022). "Interleukin (IL)-1β, IL-6, IL-10, and tumor necrosis factor (TNF)-α levels are elevated in the blood during or early in the migraine pain period compared to the non-migraine pain period." (PMID 34444772, 2021). "CSF levels of different cytokines have been reported to be lower in SLE patients with migraine compared to SLE patients with other neuropsychiatric manifestations and similar CSF IL-6 concentrations compared to controls." (PMID 34749743, 2021). "Leptin levels are also increased in correlation with pro-inflammatory cytokines IL-6 and TNF-a, which have also been found to be elevated in people with migraine." (PMID 32762643, 2020). "Proinflammatory cytokines such as IL-1β, IL-6, and TNF-α proved to have high concentrations in serum in patients with migraine, indicating that inflammation plays a significant role in migraine pathogenesis." (PMID 32516927, 2020). "IL-6 has been found to be increased in patients with TTH and migraine during headache compared to controls." (PMID 33391152, 2020). "Consistent with the higher level of IL-6, which is a strong activator of CXCL1, we found high levels of CXCL1 in all but one (patient S) migraine patients." (PMID 28900389, 2017). "For instance, some studies demonstrated an increase of proinflammatory cytokines such as IL-6, IL-2, CGRP, and TNF in migraine." (PMID 23984350, 2013). "We also demonstrate that meningeal IL-6 application can produce migraine-like behavior through activation of the ERK pathway, supporting a role for IL-6 in migraine pathophysiology." (PMID 22273495, 2012). "Our results indicate that IL-6 enhances the excitability of dural afferents likely via ERK-mediated modulation of Nav1.7 and these responses contribute to migraine-related pain behavior in vivo." (PMID 22273495, 2012). "Does it mediate the chronicity of migraine by modulating inflammatory factors such as TNF and IL-6?" (PMID 39958329, 2025). "Specifically, Mt2 appears to integrate endothelial‐derived nitric oxide production (NOS2), cytokine/chemokine release (TNF‐α/IL‐6), and neuropeptide activity (CGRP) to gate vascular tone regulation and neuronal excitability, ultimately driving migraine‐like behavioral manifestations." (PMID 41194575, 2025). "Curcumin, a natural NF-κB inhibitor, lowered IL-6 and CRP and IL-1β in these studies, and might thus help “cool off” the chronic inflammatory state in migraine." (PMID 41377228, 2025). "Moreover, in the gut, immune cells and inflammatory cytokines produced, such as interleukins (IL-1, IL-6), tumor necrosis factor (TNF-α), and C-reactive protein (CRP), seem to be involved in migraine pain, worsening the severity of attacks." (PMID 39861467, 2025). "Notably, combination nutraceutical therapies (e.g., omega-3 plus nano-curcumin) led to significant declines in IL-1β, IL-6, and TNF-α, along with fewer migraine attacks." (PMID 41377228, 2025).
migraine (continued). "Additionally, inflammatory markers such as interleukin (IL)-1β, IL-6, and tumor necrosis factor (TNF)-α have been observed to increase, particularly during migraine attack phases." (PMID 39698251, 2024). "Furthermore, elevated leptin level is thought to induce the secretion of pro-inflammatory factors (IL-6 and TNF- α) and NO that play a role in migraine through the NF-κβ signaling pathway." (PMID 38243194, 2024). "Migraine duration was positively correlated with serum HIF-1α (r = 0.712, p < 0.0001), and IL-6 levels (r = 0.476, p < 0.0001), HADS-A (r = 0.554, p < 0.0001), HADS-D (r = 0.452, p < 0.0001), and HIT-6 scores (r = 0.505, p < 0.0001) in CM patients with MOH and EM patients." (PMID 38369488, 2024). "Measurement of the PACAP as well as other inflammatory substances, like PGE2 and PGI2, interleukin-6 (IL-6), tumor necrosis factor (TNF-α) and the c-Fos gene, all of which are typically upregulated in both clinical and preclinical migraine studies, have also been utilized." (PMID 38481473, 2024). "Migraine sufferers (with and without aura) and obese patients have elevated plasma or serum concentrations of many inflammatory markers, including IL-1β, IL-6, IL-8, TNF-α, and C-reactive protein levels." (PMID 39600744, 2024). "Furthermore, according to available evidence, inflammatory factors such as interleukin (IL)‐1β, IL‐6, and tumor necrosis factor (TNF)‐α levels have also been shown to rise in patients with migraine, especially during migraine attack phases." (PMID 39055195, 2024). "The other study presented that serum IL-6, CRP, and TNF-α were significantly higher in subjects who developed chronic migraines compared to episodic migraines and controls, and a positive correlation between headache frequency and serum IL-6 and TNF-α was confirmed." (PMID 37176049, 2023). "A preclinical behavioral model of migraine was used where stimuli (PAR2 agonists: 2at-LIGRL-NH2 (2AT) or neutrophil elastase (NE); and IL-6) were applied to the mouse dura through an injection made at the intersection of the lamdoidal and sagittal sutures on the skull." (PMID 37072694, 2023). "In the sound stress migraine model, women expressed higher levels of TNF-α, IL-6, and CGRP than men, suggesting that differences in inflammatory response might be involved in the sex differences in migraine." (PMID 37176049, 2023). "Therapeutics targeting IL-6 are currently being used in humans but the efficacy of these therapeutics in migraine has not been established." (PMID 37072694, 2023). "It found that IL-1β, IL-6, and TNF-α were all higher in patients with migraine than controls." (PMID 37016284, 2023). "Moreover, another recent study confirmed that the inflammatory cytokines, including IL-1β, TNF-α, and IL-6, significant decreased after EA treatment at GB20 and GB34 in a migraine model." (PMID 37190506, 2023). "In our ex vivo preparation, pro-inflammatory cytokines (i.e., IL-6, IL-10, MCP-1, TNFα, IL-12p70, and IFNγ) are released and detectable already at basal conditions, confirming the local source of inflammatory stimuli that can trigger migraine." (PMID 35614095, 2022). "In clinical studies, it has been found that the levels in serum of IL-6 and TNF-α in migraineurs are higher than those in normal people, suggesting that neuroinflammation plays a certain role in the pathological mechanism of migraine." (PMID 35033010, 2022). "Interestingly, these three mechanisms, i.e., hyper-responses of mast cells, neuroinflammation by IL-6, and hyper-activation of ACE2 receptors, also play an important role in migraine." (PMID 34295230, 2021). "Furthermore, serum concentrations of IL-1β, IL-6, IL-8, and TNF-α were found increased during migraine attacks." (PMID 34112082, 2021). "We found that the blood serum levels of only TNF-α, but not IL-6, were significantly higher in migraine patients than in the controls." (PMID 32019484, 2020).
migraine (continued). "We found an increased serum levels or IL-6 in both FHM1 patients (D and F), as well as in the two migraine with aura patients without the genetic mutation (B and S)." (PMID 28900389, 2017). "CXCL1, like IL-6 is a pro-inflammatory and pro-nociceptive cytokine that is co-expressed in sensory neurons together with neuropeptide CGRP, which is a major migraine mediator." (PMID 28900389, 2017). "TNF alpha, IL-6, IL1 beta and IL10 were found to be increased during migraine attacks." (PMID 21331754, 2011). "For example, IL-17 was higher in CM vs. EM (9.46 ± 1.06 vs. 7.61 ± 2.12, p = 0.030), IL-6 in CM vs. non-migraine subjects (4.95 ± 2.84 vs. 1.52 ± 0.98, p = 0.016), and TNFα was higher in CM vs. non-migraine and EM subjects (0.46 ± 0.24 vs. 0.20 ± 0.05, p = 0.011 and vs. 0.20 ± 0.13, p = 0.016)." (PMID 41010614, 2025). "Mechanistic insights suggested that postoperative weight loss led to hormonal changes (e.g., lowered calcitonin gene-related peptide levels) and reductions in pro-inflammatory cytokines (such as IL-6 and TNF-α), all of which may contribute to the observed migraine relief." (PMID 41278056, 2025). "We have identified higher levels of IL-6, IL-8 and TNF-α in patients with migraine compared to healthy controls, higher levels of TGF-β and TNF-α in tension-type headache compared to healthy controls, and higher levels of IL-1β during attacks of migraine compared to the interictal period." (PMID 37016284, 2023). "Furthermore, the multivariate analysis of our data suggested that RANTES, IL6, TNFa, MCP-1, and GCSF, together with the TRP–KYN pathway, might also be important in shaping the vulnerability to migraine by modulating inflammatory and vascular processes." (PMID 35883701, 2022). "Similarly, IL-6 is elevated in migraine patients regardless of current treatment protocol and is thought to lower the pain thresholds." (PMID 23181051, 2012). "Therefore, based on the available shreds of evidence, it can be hypothesized that elevated IL-17 and IL-6 and on the other hand, reduced TGF-β and IL-10 levels might be involved in migraine pain pathophysiology certainly through exacerbating inflammatory responses." (PMID 33653409, 2021). "Although there is currently no direct link between Nav1.7 and migraine, these findings suggest that an IL-6/Nav1.7 signaling axis can be an important mediator of headache pain and that drugs targeting IL-6 signaling may have efficacy in the treatment of migraine headache." (PMID 22273495, 2012). "Although gut microbiota profiles differed significantly between M + G and M + noG patients, plasma levels of migraine markers (CGRP and PGE2) and inflammatory indices (IL-1β, IL-6, NF-κB, TNF-α) did not." (PMID 41454664, 2026). "Significantly increased ictal IL-1β, IL-6 and TNF-α serum concentrations were measured in migraine patients with/without aura compared to post-ictal (after 1 week treatment) and healthy subjects not clearly indicative for a predictive value." (PMID 30795781, 2019). "However, given that IL-6 levels were similarly raised in both NDPH and CM in this study suggests that it could be a non-specific reaction to pain rather than unique to migraine." (PMID 40236898, 2025).
breast tumor (146 papers, 1999 to 2026). "Analyses of human breast tumor samples demonstrated that the expression of IL-6 is elevated in the early stage of breast tumors and is positively associated with advanced tumor stages, suggesting a critical role in breast tumor metastasis." (PMID 37237509, 2023). "The direct migration model instead evidenced that high stiffness in the breast tumor is linked to high IL‐6 activity, an important factor for metastasis initiation as well as osteolysis." (PMID 36351739, 2023). "In agreement with our study, Chang and associates have recently shown the increased levels of IL-6 at the leading edge of invasive human breast tumors." (PMID 26258407, 2015). "Finally, its association with inflammatory factors such as COX2, IL-6 and TNFα provides further evidence that AIF1v1 is a key regulator of inflammation in the breast tumor microenvironment and interacts with a wide variety of cytokines and adipokines." (PMID 30386176, 2018). "A 2022 study noted that an IL-6/IL-10 mRNA expression signature in breast tumors was paradoxically linked to better survival in early-stage patients, hypothesizing that some level of immune activation (IL-6) combined with IL-10-mediated resolution might be beneficial." (PMID 41007766, 2025). "Nerve ablation revealed that breast tumor innervation contributes to tumor growth and promotes a proinflammatory microenvironment by inducing interleukin-6 (IL-6) production and macrophage recruitment." (PMID 40243726, 2025). "There is a significant positive correlation between IL-6 and pSTAT3 levels in primary breast tumors, as IL-6 triggers the activation of STAT3 signaling." (PMID 39893499, 2025). "Analysis of human breast tumors showed that the IL-6/JAK/STAT3 pathway is enriched in ER + ILC compared to ER + NST." (PMID 40597443, 2025). "IL-6 is a pleiotropic pro-inflammatory cytokine that has emerged as a central player linking chronic inflammation to breast tumor progression." (PMID 41007766, 2025). "The IRF1 pleiotropic activity is indicated by the increased expression of IRF1 in HER2+ breast tumor basal cells that in contrast to FB2 cells, were associated with the IL6-JAK-STAT3 signaling pathway." (PMID 40862725, 2025). "In more advanced stages of ductal carcinoma, tumor tissues are infiltrated by abundant concentrations of T cells and M2 macrophages, which produce large amounts of IL-6, promoting metastasis of breast tumor cells." (PMID 38793599, 2024). "IL-10 and IL-6 are both known to promote breast tumor growth and are often central to breast tumorigenesis and metastasis." (PMID 38397942, 2024). "T. gondii transcriptionally regulates several signaling pathways by altering the hub genes such as BRCA1, MYC and IL-6, which can inhibit the breast tumor growth and migration, hinting at a potential therapeutic strategy." (PMID 38654350, 2024). "Mice with breast tumors treated with EHop-016 significantly decreased the proinflammatory cytokine Interleukin-6 (IL-6) from plasma and the TME." (PMID 37397366, 2023). "For poorly differentiated breast tumors, an increase in the content of IL-1β, IL-2, IL-6, and IL-10 was observed, while the content of the rest decreased compared to the control group, but to a lesser extent than for highly differentiated tumors." (PMID 36286034, 2022). "This exposure to IL-6 leads to the chronic induction of STAT3pY705, which promotes further growth and invasion of breast tumor cells." (PMID 35626741, 2022). "Our scRNA-seq and FACS analyses revealed that OSM and OSMR have a unique expression pattern in breast tumors, compared with other members of the IL-6 cytokine family." (PMID 35192545, 2022). "This upregulation in IL-6 expression via NF-κB signaling in the breast tumor microenvironment leads to recruitment of neutrophils and myeloid-derived suppressor cells (MDSCs) to further promote tumor cell invasiveness and metastasis to the lung." (PMID 35053592, 2022).